CDK9 (cyclin dependent kinase 9)
Diseases named in the same sentence as CDK9 in open-access papers (continued):
Sharing a sentence is not in itself a finding about the gene and the disease.
prostate carcinoma (continued). "We earlier performed a comprehensive screen to discover compounds that sensitize prostate cancer cells to OGT inhibitors, and this work led to the discovery of combinatorial lethal interaction between OGT and CDK9 inhibitors that is specific to prostate cancer cells." (PMID 35164752, 2022). "Moreover, CDK9 is a promising prognostic marker and therapeutic target in cancers, including activity castration-resistant prostate cancers (CRPCs) models." (PMID 34066883, 2021). "In addition, cyclin-dependent protein kinase 9 (CDK9) is a druggable target for prostate cancer because CDK9 can not only phosphorylate AR and activate AR transcriptional activity but also target anti-apoptotic proteins." (PMID 32456317, 2020). "The interconnected functions of CDK9 and BRD4 have led to the evaluation of combinatorial targeting of both factors as a cancer therapy, a concept we explored in prostate cancer." (PMID 39117800, 2024). "Gain or amplification of the CDK9 gene is common in prostate cancer, particularly in CRPC, and copy number alterations explain, at least in part, increased CDK9 mRNA expression." (PMID 39117800, 2024). "The activity of an orally bioavailable CDK9 inhibitor, CDKI-73, was evaluated in prostate cancer cell lines, a xenograft mouse model, and patient-derived tumor explants and organoids." (PMID 39117800, 2024). "Our work demonstrates that CDK9 inhibition disrupts multiple oncogenic pathways and positions CDKI-73 as a promising therapeutic agent for prostate cancer, particularly aggressive, therapy-resistant subtypes." (PMID 39117800, 2024). "One kinase regulator of AR is cyclin-dependent kinase 9 (CDK9), which phosphorylates AR at serine 81 (pSer81-AR), a modification that enhances AR’s transcriptional activity and prostate cancer cell growth." (PMID 39117800, 2024). "Based on these data, both prostate cancer and CRPC cells can be sensitized to CDK7 inhibitors by targeting CDK9." (PMID 36401094, 2023). "Next, we analyzed TCGA prostate cancer data and found that the expression of CDK9 and MED1 was positively correlated in prostate cancer." (PMID 35394046, 2022). "Accordingly, we show that combined inhibition of CDK9 and either OGT or MRE11 induces robust DNA damage in prostate cancer cells." (PMID 35164752, 2022). "Combined inhibition of CDK9 and OGT or MRE11 further decreases RNA polymerase II activity, induces DNA damage signaling, and blocks the survival of prostate cancer cells." (PMID 35164752, 2022). "The combinatorial lethality was observed in prostate cancer cells treated with an OGT inhibitor (OSMI-2) and a CDK9 inhibitor (AT7519)." (PMID 35708495, 2022). "Therefore, the use of CDK7 and CDK9 inhibitors in combination with immune checkpoint inhibitors may represent a powerful therapeutic combination, particularly for tumours displaying a “cold” immune microenvironment, as is the case of prostate cancer." (PMID 35568739, 2022). "Inhibition of cyclin-dependent kinase 9 (CDK9), an RNA-polymerase II regulator, activates AMPK to increase FAO in prostate cancer cells." (PMID 33291682, 2020). "CDK9 inhibitor II, CAN508 is an arylazopyrazole compound that inhibits CDK9 with 38-fold selectivity for CDK9/cyclin T over other CDK/cyclin complexes and regulates CDK9 mediated c-MYC and androgen receptor transcription in breast and prostate cancers." (PMID 28404924, 2017). "Strikingly, the combined inhibition of CDK7 and CDK9 led to an over 80% decrease in proliferation in the prostate cancer and CRPC cells but did not affect the cell lines derived from normal prostate epithelia." (PMID 36401094, 2023). "We hypothesized that CDK9 inhibition affects O-GlcNAcylation of CDK9 because combined inhibition of OGT and CDK9 is toxic to prostate cancer cells, OGT inhibition decreases phosphorylation of CDK9 and CDK9 is known to be O-GlcNAcylated." (PMID 35164752, 2022).
prostate carcinoma (continued). "Finally, supplementing prostate cancer cell lines with vitamin B5 in the presence of CDK9 inhibitor mimics the effects of co-targeting OGT and CDK9." (PMID 35708495, 2022). "Indeed, combined treatment of prostate cancer cells with OGT inhibitor and the CDK9 inhibitor NVP2 induced the accumulation of p-H2AX in PC and CRPC cells but not in the normal prostate cells." (PMID 35164752, 2022). "First, we confirmed that combined inhibition of OGT and CDK9 selectively inhibits proliferation of prostate cancer cells but does not have effects on normal prostate cells, as previously reported." (PMID 35164752, 2022). "Here, we showed that this interaction is explained to large extend due to the CDK9 inhibitor-induced DNA damage, which is activated only in the prostate cancer but not in normal prostate cells." (PMID 35164752, 2022). "To test if OGT regulates MRE11 chromatin-association, we isolated nuclear/cytosolic- and chromatin-fractions from prostate cancer cells treated with CDK9 inhibitor in the presence and absence of the OGT inhibitor OSMI-4." (PMID 35164752, 2022). "Interestingly, combinatorial targeting of OGT and CDK9 is selectively toxic to prostate cancer cells but not to normal prostate cells." (PMID 35708495, 2022). "We hypothesized that OGT activity is remodeled in response to CDK9 inhibitor treatment because combined inhibition of OGT and CDK9 is toxic to prostate cancer cells, OGT activity is remodeled in response to stress and OGT-dependent glycosylation alters protein function." (PMID 35164752, 2022). "First, we treated prostate cancer cells for four hours with increasing doses of the highly specific inhibitor against each kinase, to establish doses that robustly decrease RNA Pol II phosphorylation: 500 nM for CDK7 and CDK12/13 inhibitors and 20 nM for CDK9 inhibitor were found to achieve this." (PMID 35164752, 2022). "In addition to over-riding programmed cell death responses via upregulation of anti-apoptotic factors, CDK9 also promotes the expression and/or activity of oncogenic transcription factors such as MYC, NF-κB, BRD4, and STAT3, all of which are established drivers of prostate cancer progression." (PMID 39117800, 2024).
hepatocellular carcinoma (21 papers, 2011 to 2026). A malignant tumor that arises from hepatocytes. "This inhibition of mitophagy by CDK9 inhibitors contributes to increased mitochondrial dysfunction, ultimately promoting apoptosis in hepatocellular carcinoma." (PMID 39403142, 2024). "A high level of CDK9 expression concurrent with a downregulation of miRNA-206, an inhibitor of translation from CDK9 mRNA, was noted in hepatocellular cancer cell lines." (PMID 34041038, 2021). "Gene silencing using a shRNA library identified the requirement of CDK9 for the sustained proliferation of hepatocellular cancer cells and their dependence on MYC." (PMID 34041038, 2021). "Pang et al48 indicated that miR‐206 overexpression suppressed hepatocellular carcinoma cell growth by regulating CDK9 expression." (PMID 30156374, 2018). "CDK9 as a therapeutic target for MYC driven cancer was demonstrated in a shRNA library screening in which CDK9 was required for the aberrant proliferation of MYC overexpressing hepatocellular carcinoma cell lines." (PMID 27486754, 2016). "We demonstrated the interaction between ASF1B and CDK9 in hepatocellular carcinoma cells." (PMID 35087760, 2021). "In addition, miR-206 can also restrain the growth of hepatocellular carcinoma by targeting cyclin-dependent kinase 9 (CDK9)." (PMID 33145343, 2020). "CDK9 is a potential target as it is part of P-TEFb, is necessary for proliferation and maintenance of MYC-overexpressing hepatocellular carcinoma, and is required for maintenance of gene silencing in several cancer cell lines." (PMID 33322239, 2020). "CDK9 inhibitors demonstrate efficacy in downregulating MYC transcripts and Myc stability across hepatocellular carcinoma, mixed-lineage leukemia, diffuse large B-cell lymphoma, acute myeloid leukemia, and pancreatic cancer." (PMID 33322239, 2020). "Xylocydine is a novel cyclin-dependent kinase (cdk) inhibitor that induces apoptosis in hepatocellular carcinoma (HCC) cells by inhibiting Cdk1, Cdk2, Cdk7, and Cdk9 activities." (PMID 23344045, 2013). "CDK9 inhibitors repress the SIRT1-FOXO3-BNIP3 axis and the PINK1-PRKN pathway, thereby inhibiting mitophagy initiation and promoting mitochondrial dysfunction in hepatocellular carcinoma, which disrupts mitochondrial homeostasis and induces apoptosis." (PMID 40855568, 2025). "Inhibition of CDK9 can block the initiation of PINK1-PRKN-mediated mitochondrial phagocytosis by regulating the SIRT1-FOXO3-BNIP3 axis and enhance the therapeutic effect of mitochondrial dysfunction in hepatocellular carcinoma." (PMID 38012584, 2023). "Moreover, the authors found that enforcing MYC expression in human hepatocellular carcinoma‐derived cells increased the sensitivity to PHA‐767491, a CDK9‐inhibitory tool compound." (PMID 36214609, 2022). "Furthermore, the silencing of CDK9 inhibited MYC-dependent liver tumorigenesis in a mouse model and suppressed the proliferation of xenografts of murine and human hepatocellular cancer cells." (PMID 34041038, 2021). "However, it is unknown whether CDK9 is involved in the miR‐206‐mediated growth suppression of hepatocellular carcinoma (HCC) cells." (PMID 28940993, 2017).
ovarian carcinoma (19 papers, 2014 to 2025). A malignant neoplasm originating from the surface ovarian epithelium. "The study confirmed that CDK9 is required for cell survival and that ovarian cancer may be susceptible to CDK9 inhibition strategy." (PMID 25277198, 2014). "CDK9 expression was also significantly higher in the patient-paired metastatic and recurrent tissue when compared to primary ovarian cancer tissue." (PMID 35326643, 2022). "A tissue microarray of 441 epithelial ovarian cancer (EOC) samples was used to study the expression of CDK9 immunohistochemically and their clinico-pathological associations were determined." (PMID 34011401, 2021). "We also examined the immunohistochemical expression of CDK9 in 4 ovarian cancer cell lines (SKOV-3, OVSAHO, OVCAR-3 and COLO-704) and found that it was over-expressed in all these cell lines." (PMID 34011401, 2021). "Another study in wild-type BRCA1 ovarian cancer cells demonstrated that the combined treatment of Olaparib and the CDK9 inhibitor CDKI-73 suppressed colony formation and induced apoptosis, and additionally reduced tumor growth in a xenograft mouse model." (PMID 34207158, 2021). "Recently, cyclin dependent protein kinase 9 (CDK9) has been recognized as a crucial cell cycle regulator and important player in several cancers including ovarian cancer." (PMID 34011401, 2021). "We herein report the cellular mechanism of a novel CDK9 inhibitor CDKI-73 in an ovarian cancer cell line (A2780)." (PMID 25277198, 2014). "In addition, CDK9 inhibition was proven effective in ovarian cancer, esophageal adenocarcinoma, and pancreatic cancer." (PMID 36979907, 2023). "Similarly, CDK9 inhibition sensitised a syngeneic ovarian cancer model to anti-PD-1 therapy, by derepressing endogenous retroviruses and inducing an interferon response." (PMID 35568739, 2022). "Therefore, we conducted this study to evaluate the incidence of CDK9 overexpression in Middle Eastern epithelial ovarian cancer (EOC) patient specimens and explore its predictive as well as prognostic value in this patient cohort." (PMID 34011401, 2021). "Moreover, recent knockdown studies in A2780 ovarian cancer cells revealed that the down‐regulation of CDK9 affected the oncogenic translation via the Mnk‐eIF4E axis." (PMID 31398271, 2019). "We herein report that CDKI-73 targets both CDK9- and eIF4E-related pathways and it may serve as an effective therapeutic agent for the treatment of ovarian cancer, as well as a range of other cancers." (PMID 25277198, 2014). "Additionally, LDC000067 treatment led to significant reductions of clonogenicity, 2D migration and 3D spheroid formations of two ovarian cancer cell lines—SKOV-3 and OVCAR-8, once again highlighting the significance of CDK9 in the poor prognosis of ovarian cancer." (PMID 34062779, 2021). "Previously, we also showed that CDK9 inhibition, combined with anti-PD1 treatment, synergistically reduced tumor burden, and prolonged survival, in an ovarian cancer model." (PMID 38172923, 2024). "We tested combinations of small-molecule CDK9 and/or BRD4 inhibitors in conjunction with Carboplatin and Paclitaxel and observed a synergistic inhibition of HGSOC ovarian cancer cell growth." (PMID 38201534, 2023). "However, the expression of CDK9 in ovarian cancer from Middle Eastern ethnicity remains unknown." (PMID 34011401, 2021). "The authors also examined the anti-tumor effects of CDK9 inhibition in an ovarian cancer mouse model treated with SNS-032 and observed reactivation of ovarian-cancer specific hypermethylated TSGs, decreased tumor burden, and prolonged survival." (PMID 34207158, 2021). "In previous studies, the synergetic effect of olaparib, a PARP inhibitor, combined with CDKI-73, a CDK9 inhibitor, was reported in BRCA1-proficient ovarian cancer cells; the combination resulted in a reduction of BRCA1 expression and recruitment to DNA damage sites." (PMID 40713627, 2025).
ovarian carcinoma (continued). "Consistent with our previous finding in A2780 ovarian cancer cell line, CDK9 knockdown did not affect the Mnk1 protein in HCT 116 cells." (PMID 31398271, 2019). "Additionally, cyclin-dependent kinase 9 (CDK9) inhibition with toyocamycin activated the SWI/SNF catalytic subunit BRG1 and synergized with DNMT inhibition to de-repress endogenous retroviral elements and interferon signaling, sensitizing an in vivo ovarian cancer model to PD-1 immunotherapy." (PMID 36497341, 2022). "Moreover as evidenced previously in ovarian cancer lines and triple negative breast cancer, as well as in this study, CDK9 expression can be downregulated by dinaciclib, which may explain the observed augmentation of EV-T responses by the inhibitor." (PMID 32375399, 2020). "Thus, whereas ovarian cancer cell lines can be clearly segregated into PD0332991-sensitive and resistant lines, IC50 values for current CDK2 inhibitors show a continuum within a narrow dose range that may be the result of non-cell cycle CDKs affected by SNS032 (CDK9) and dinaciclib (CDK5, 9)." (PMID 25557169, 2015).
osteosarcoma (17 papers, 2011 to 2025). A usually aggressive malignant bone-forming mesenchymal neoplasm, predominantly affecting adolescents and young adults. "Some of the major types of cancers associated with CDK9 overexpression are myeloma, osteosarcoma, lung, breast, prostate cancer, and many more, which are explained here." (PMID 40361480, 2025). "CDK9 expression had been implicated in the prognosis and resistance to anti-cancer therapeutics in a large number of cancer types like those of breast, lung, prostate, endometrium, apart from melanoma, osteosarcoma, myeloid leukemia, soft tissue sarcomas etc.." (PMID 34062779, 2021). "The most significant predictor of disease outcome for patients with osteosarcoma is the percentage of tumor necrosis following neoadjuvant chemotherapy, and it is inversely connected with CDK9 expression." (PMID 40361480, 2025). "In osteosarcoma, CDK9 knockdown with siRNA and CDK9 activity suppression using an inhibitor reduced cell growth and triggered apoptosis." (PMID 40361480, 2025). "MALAT1 regulates the expression of the cell cycle protein-dependent kinase 9 (CDK9) by sponging miR-206, thereby controlling the progression of osteosarcoma." (PMID 36903369, 2023). "CDK9 is an emerging therapeutic target for cancer treatment, and upregulation of CDK9 has been identified in several cancers, such as osteosarcoma, melanoma, and gastric cancer." (PMID 35088192, 2023). "Cyclin-dependent kinase 9 (CDK9) can predict the prognosis of osteosarcoma, bladder cancer and other tumors, and can be used for targeted treatment of glioblastoma." (PMID 37302999, 2023). "The overexpression of MIF/CDK9/c‐Myb can significantly reverse the therapeutic effect of 4‐IPP on osteosarcoma." (PMID 35060345, 2022). "In one study, osteosarcoma cells pre-treated with either the CDK9 inhibitor flavopiridol or 5,6-dichloro-1-β-D-ribofuranosylbenzimidazole demonstrated impaired cell cycle recovery following treatment with hydroxyurea." (PMID 34207158, 2021). "Previous studies have also shown that inhibition of CDK2/9 in triple-negative BC cells and CDK9 inhibition in osteosarcoma cells decreased migration by preventing phosphorylation of CDK-mediated Smad3 and RNA POL-ll in triple-negative BC33,34." (PMID 33723248, 2021). "Clinically, it has been observed that CDK9 is overexpressed in many cancer types, such as pancreatic cancer, osteosarcoma, synovial sarcoma, and endometrial cancer, and that a high CDK9 expression correlates with poor patient prognosis." (PMID 34207158, 2021). "In concordance with our study, the overexpression of CDK9 and its prognostic value have been documented in several human cancers, including endometrial cancer, chordoma, osteosarcoma, pancreatic cancer and colon cancer." (PMID 34011401, 2021). "CDK9 expression was also higher in osteosarcoma cell lines, as compared to the osteoblast cell line HOB-c." (PMID 34062779, 2021). "Although the role of lncRNA-MALAT1 in miR-206/CDK9 axis-mediated osteosarcoma proliferation remains unclear, the findings indicate that the MALAT1/miR-206/CDK9 axis may provide novel insights into the biological mechanisms of osteosarcoma progression." (PMID 36903369, 2023). "In this study, we provide evidence that the MIF inhibitor 4‐IPP has an anti‐tumour effect on osteosarcoma by promoting the degradation of the MIF protein and inhibiting the transcription of c‐Myb through hampering the formation of the downstream NF‐κB/CDK9 complex in osteosarcoma." (PMID 35060345, 2022). "Hence, it is concluded that 4‐IPP hinders osteosarcoma cell development by blocking the formation of the p65/CDK9 transcriptional complex, thereby reducing the transcription of its direct target gene c‐Myb." (PMID 35060345, 2022). "Further studies were conducted to clarify whether the overexpression of CDK9 could rescue the anti‐tumour effect of 4‐IPP on osteosarcoma." (PMID 35060345, 2022).
osteosarcoma (continued). "Co-immunoprecipitation confirmed that CDK9 interacts with both GBP1 and STAT3 in osteosarcoma cells." (PMID 40975978, 2025). "CDK 9 overexpression also increased proliferation of human osteosarcoma cell line U20S2, while CRK, CDK9, DCAF7, NEK6, GNB1, SPOP, and WW2 also increased proliferation in mouse fibroblasts." (PMID 21629697, 2011). "Likewise, increased expression of CDK9 was observed in osteosarcoma cells lines compared to normal osteoblasts and ~67% of osteosarcoma patient tumors (from a TMA containing 70 OS) had elevated CDK9." (PMID 32344731, 2020).